PCSK9 (proprotein convertase subtilisin/kexin type 9)
Diseases named in the same sentence as PCSK9 in open-access papers (continued):
Sharing a sentence is not in itself a finding about the gene and the disease.
atherosclerosis (continued). "Given the association of plaque stabilization and regression with LDL levels, it was logical to assume that the greater, immediate LDL reduction provided by the PCSK9 inhibitor use could greatly influence atherosclerosis progression, as was initially hypothesized in ACS patients." (PMID 39125547, 2024). "Future therapies may involve combining strategies targeting the ECM with existing lipid-lowering therapies (e.g., statins or PCSK9 inhibitors) or anti-inflammatory drugs to provide a more comprehensive approach to treating atherosclerosis and improving cardiovascular outcomes." (PMID 39596083, 2024). "In addition, in the study of PCSK9 preparations that are now widely used in clinical practice, it was found that PCSK9 mediates lipophagy and promotes lipid degradation, making it an important mechanism for the treatment of atherosclerosis." (PMID 39165945, 2024). "This highlights the important role of local PCSK9 expression and action in the vasculature, particularly as ECs, VSMCs as well as macrophages, and other immune cells are all involved in the development and progression of atherosclerosis and other vascular diseases." (PMID 38886277, 2024). "In addition, in an ovariectomized ApoE -/- mice model, it was demonstrated that ESRα inhibited the synthesis and secretion of proprotein convertase subtilisin/kexin type 9 (PCSK9) and subsequently lowered the accumulation of cholesterol and triglyceride to prevent post-menopausal atherosclerosis." (PMID 36833280, 2023). "In addition, PCSK9 deletion in mice lowers the occurrence of atherosclerosis according to LDL-R." (PMID 36935878, 2023). "This work suggests that PCSK9 may contribute to atherosclerosis beyond lipid metabolism." (PMID 37854060, 2023). "Similarly, the randomized, controlled HUYGENS study was conducted to assess the impact of the proprotein convertase subtilisin kexin type-9 (PCSK-9) inhibitor evolocumab on atherosclerosis regression in patients treated with the maximum statin dose (NCT03570697)." (PMID 36983851, 2023). "Indeed, it has recently been suggested that high levels of circulating PCSK9 could directly promote the occurrence and progression of atherosclerosis, independently of the LDL-C levels." (PMID 38115042, 2023). "Additionally, the Further Cardiovascular Outcomes Research with PCSK9 Inhibition in Subjects with Elevated Risk trial studied patients with clinical evidence of atherosclerosis and LDL-C levels of 70 mg/dL or non-HDL-C of 100 mg/dL." (PMID 37784041, 2023). "Furthermore, we describe the specific molecular mechanism underlying the PCSK9 and NLRP3 inflammasome signaling pathway in atherosclerosis and cells related to inflammation, including vascular smooth muscle cells (VSMCs), endothelial cells (ECs) and macrophages (MФ)." (PMID 36911736, 2023). "Moreover, The European Collaborative Project on Inflammation and Vascular Wall Remodeling in Atherosclerosis-Intravascular Ultrasound (ATHEROREMO-IVUS) study showed that serum PCSK9 levels were in relation to the absolute volume of inflammatory plaque and necrotic core tissue." (PMID 35252378, 2022). "The PCSK9-derived platelet was found to promote platelet aggregation, thrombus formation, monocyte migration, and monocyte differentiation into foam cells, all of which contributed to the occurrence of atherosclerosis progression-induced coronary artery disease." (PMID 35207479, 2022). "Thus, the high plasma level of PCSK9 and the subsequent atherosclerosis process may explain, at least partly, the high cardiovascular mortality rate observed in HD patients studied." (PMID 35354429, 2022). "The human recombinant of PCSK9 and anti-PCSK9 were then used to evaluate the effect on thrombus formation, platelet aggregation, monocyte differentiation into foam cells, and monocyte migration, by which all led to the development of atherosclerosis progression-induced coronary artery disease." (PMID 36005422, 2022).
atherosclerosis (continued). "Indeed, it has recently been suggested that PCSK9 could promote atherosclerosis progression by stimulating proinflammatory cytokine production and promoting oxidative stress within the atherosclerotic lesions, independently of the LDL-C levels." (PMID 35454151, 2022). "Hence, here, we address our current understanding of the pathophysiological process involved in atherosclerosis-induced myocardial infarction (MI) through platelet activation and highlight the molecular mechanisms used by PCSK9 in regulating platelet activation." (PMID 35207479, 2022). "The observation that PCSK9 is involved in the pathophysiology of inflammation, heart disease, atherosclerosis, nephrotic syndrome, hepatic steatosis, infections, and cancer metastases might positively influence on the therapeutic approach to those diseases in the future." (PMID 35323699, 2022). "The idea of combining lipid-lowering therapeutics with anti-inflammatory drugs is getting increasingly recognized, and targeting GsdmD in combination of LDL lowering therapies such as statins or PCSK9 antibody may serve as potential therapeutic to treat atherosclerosis and CVD." (PMID 34395445, 2021). "Furthermore, recent studies suggested that PCSK9 could accelerate atherosclerosis through mechanisms beyond the degradation of the hepatic LDL receptor." (PMID 33407555, 2021). "Thus, PCSK9 provides a potential target to search for new small molecules that may potentially be developed as therapeutic agents in reducing the progression of atherosclerosis." (PMID 34443682, 2021). "Inhibiting PCSK9 may have anti-atherogenic properties in HHcy-accelerated atherosclerosis." (PMID 34660746, 2021). "Hence, the benefits observed from PCSK9 inhibitory therapies may not only be induced by its plasma lipid-lowering capacities but also by reducing the impact of several other mechanisms in which PCSK9 is involved that are actively promoting atherosclerosis." (PMID 33834043, 2021). "Unfortunately, the information on PCSK9 interactome is still limited and further investigations on the role of PCSK9's activity on different signaling pathways are still needed to generate a clear vision of PCSK9 full potential during atherosclerosis progression." (PMID 33834043, 2021). "However, little is known about the role of PCSK9 and its inhibition in Hcy-induced atherosclerosis." (PMID 34660746, 2021). "Beyond its role in cholesterol homeostasis, PCSK9 is prevalent in human macrophages, smooth muscle cells, endothelial cells, and cardiomyocytes, with a local effect that can regulate vascular homeostasis and atherosclerosis, suggesting a different role of PCSK9 in the heart." (PMID 34439528, 2021). "Moreover, experimental studies indicate that PCSK9 might independently accelerate atherosclerosis by enhancing inflammation, endothelial dysfunction, and hypertension." (PMID 33173529, 2020). "Besides, Qu can also affect the expression of LXRα and ABCA1 through the p38-dependent pathway, proprotein convertase subtilisin/kexin type 9 (PCSK9) pathway, and cholesterol 7 alpha-hydroxylase (CYP7A1) pathway to promote cholesterol efflux and reduce the risk of atherosclerosis." (PMID 32565865, 2020). "Therefore, this study was conducted to determine whether aerobic exercise training contributes to treat atherosclerosis via PCSK9 and LOX-1 in balloon-induced common carotid arteries of high-fat-diet rats." (PMID 32325897, 2020). "However, there has been no report on the relationship between PCSK9 nonsense mutations and early atherosclerosis." (PMID 33255270, 2020).
atherosclerosis (continued). "Our in vitro and in silico study established that Ginkgolide B alleviated the Ox-LDL-induced inflammatory cascades and altered lipid metabolism in HUVECs by suppressing the PCSK-9 and, thus, could be established as a treasured alternative therapeutic candidate in the atherosclerosis management." (PMID 31281844, 2019). "However, the relationship between circulating PCSK9 and pathophysiological mechanism of atherosclerosis is unknown." (PMID 30816133, 2019). "However, one can envision a new paradigm of cardiovascular prevention for high risk patients in which a short-term of very aggressive LDL-C lowering with PCSK-9 inhibitors in addition to statin therapy is used to stabilize the atherosclerosis process at a vulnerable young age." (PMID 28979904, 2016). "In addition, other evidences suggest that lupin protein can modulate the production of proprotein convertase subtilisin/kexin type 9 (PCSK9), a protein which is correlated to atherosclerosis progression and is, therefore, a novel target for hypocholesterolaemic drugs." (PMID 27455315, 2016). "Hence, inhibition of PCSK9 has been considered a promising drug target for atherosclerosis." (PMID 26431033, 2015). "Therefore, PCSK9 has been considered as another target for dyslipidemia and atherosclerosis." (PMID 24533584, 2014). "Elevated LDL‐C levels drive atherosclerosis, and intensive LDL‐C lowering therapies, including statins and PCSK‐9 inhibitors, are highly effective." (PMID 41543036, 2026). "AAV-PCSK9 injection, which induces sustained PCSK9 expression, LDL receptor downregulation, and hyperlipidemia, combined with a high-fat diet, rapidly induces atherosclerosis in C57BL/6J mice." (PMID 40237461, 2025). "Studies have shown that PCSK9 directly enhances atherosclerotic lesions through an LDL-independent mechanism, leading to vascular inflammation and atherosclerosis." (PMID 40354375, 2025). "Finally, considering our hypothesis of Pcsk9 and Bhlhe40 as mechanistic mediators of the SNP effect, we tested the effect of in vivo knockdown of these genes on the SNP-mediated effect on cholesterol and atherosclerosis through AAV8 vectors." (PMID 40591411, 2025). "The FOURIER trial (n=27,564) on individuals with atherosclerosis and advanced CKD demonstrated greater reduction in the composite of CV death, MI, and stroke with evolocumab (PCSK9 inhibitor) treatment." (PMID 40861717, 2025). "Among them, PCSK9 and IL6R are already being investigated as therapeutic targets for atherosclerosis." (PMID 40649979, 2025). "This study was conducted to explore how red watermelon (Citrullus lanatus) consumption modulates the lipid profile, and the expression of PCSK9, LOX-1, CD36, ROS, TNFα, and ABCA1 so that it can inhibit the development of atherosclerosis." (PMID 40699832, 2025). "This review synthesizes current evidence on the interplay between inflammation, oxidative stress, and atherosclerosis in CKD, with a special focus on emerging molecular biomarkers—PCSK9, EPHX2, AOPPs, and TBARSs—and their integration with clinical indices." (PMID 40868936, 2025). "Path analysis demonstrates the interrelationships of Citrullus lanatus (CL), PCSK9, LOX-1, CD36, ABCA1, and foam cell (FC) formation in atherosclerosis." (PMID 40699832, 2025). "This study focuses on uncovering the effects of proprotein convertase subtilisin/kexin type 9 (PCSK9) inhibitors in attenuating arterial stiffness in patients with acute coronary syndrome (ACS) and atherosclerosis." (PMID 40821628, 2025).
atherosclerosis (continued). "Another important lncRNA is lincRNA-p21, which acts as a molecular sponge for miR-221 to induce de-acetylation of the PCSK9 promoter sequence through SIRT1, thereby inhibiting atherosclerosis development." (PMID 40764605, 2025). "PCSK9 has also been shown to activate TLR4 signaling pathways, linking it directly to innate immune responses and atherosclerosis." (PMID 40868936, 2025). "The glucocorticoid receptor coding SNP rs6190 increases cholesterol through PCSK9 and BHLH40 upregulation, promoting atherosclerosis in a sexually dimorphic manner." (PMID 40591411, 2025). "CRISPR-Cas9 has changed PCSK9 expression in hepatocytes, thereby reducing LDL cholesterol and so decreasing atherosclerosis in preclinical animals." (PMID 40430848, 2025). "Recent findings suggest that PCSK9 interacts with the NLRP3 inflammasome, potentially influencing the inflammatory processes involved in atherosclerosis progression." (PMID 40426881, 2025). "This study aimed to explore the effects of red watermelon extract on the expression of PCSK9, LOX-1, ROS, TNFα, CD36, and ABCA1 in a Wistar rat model of atherosclerosis." (PMID 40699832, 2025). "Primarily, studies have suggested that certain antigens, such as ox-LDL, ApoB-100, CETP, PCSK9, HSP60, MHC-II-derived peptides, and interleukins, are involved in atherosclerosis." (PMID 40823653, 2025). "RNAi inhibition of PCSK9 significantly reduces LDL-C levels and inhibits the course of atherosclerosis in ApoE−/− mice." (PMID 39857372, 2024). "Thus, it is speculated that the principal effect of PCSK9 inhibitors on halting atherosclerosis progression is caused by plaque stabilization rather than lumen increase followed by improvement in coronary hemodynamics." (PMID 39595002, 2024). "Ample evidence has demonstrated that PCSK9 can elevate plasma LDL-C levels, contributing to the progression and development of atherosclerosis." (PMID 38796450, 2024). "This implicates the potential of PAC1-specific agonist drugs against atherosclerosis even beyond statins and PCSK9 (proprotein convertase subtilisin/kexin type 9) inhibitors." (PMID 39769009, 2024). "Herein, we presented the current evidence on the structure, functions, and roles of TLR4, PCSK9, and LOX-1 in atherosclerosis." (PMID 38445291, 2024). "Statins and proprotein convertase subtilisin/kexin type 9 (PCSK9) inhibitors have proven to be safe, effective, and well-established treatments for atherosclerosis." (PMID 38375475, 2024). "The inflammatory signaling pathways involved in the occurrence and progression of atherosclerosis, including the NLRP3 inflammasome receptor, Toll-like receptor, proprotein convertase subtilisin/kexin type 9 (PCSK9), Notch and Wnt signaling pathways." (PMID 39092226, 2024). "Medications like statins, PCSK9 inhibitors, and ezetimibe can lower LDL cholesterol, lowering the chance of cardiovascular events and atherosclerosis." (PMID 38716006, 2024). "Elevated LDL-C levels in the blood significantly contribute to atherosclerosis, underscoring the importance of lowering LDL-C, wherein PCSK9 plays a crucial role in this molecular mechanism." (PMID 39770423, 2024). "Recently, much attention has been paid to the interaction between PCSK9 and LRP5/6 in the development and progression of atherosclerosis." (PMID 36970356, 2023). "In this review, we summarize the current findings related to the interactions between PCSK9 and the NLRP3 inflammasome in atherosclerosis." (PMID 36911736, 2023).
atherosclerosis (continued). "Clinical therapeutic strategies for atherosclerosis are mainly focused on maintaining a lower level of blood LDL by statins, NPC1L1 and PCSK9 inhibitors." (PMID 37963874, 2023). "The Global Assessment of Plaque Regression with a PCSK9 Antibody as measured by Intravascular Ultrasound trial, known as the GLAGOV trial, investigated the effect of PCSK9 inhibition on atherosclerosis." (PMID 36935878, 2023). "With increasing circulating levels of PCSK9 the hepatic LDL clearance is reduced, which promotes atherosclerosis." (PMID 37759784, 2023). "FURIN is also involved in activation of proBNP, PCSK9, and ANGPTL, which each contribute to the development of atherosclerosis." (PMID 37940228, 2023). "Despite the fact that PCSK9 is one of the most important molecules in the metabolism of LDL cholesterol, its effects on the atherosclerosis process go far beyond regulating the concentration of LDL cholesterol." (PMID 36768292, 2023). "First, the protective effect of PCSK9 inhibition on atherosclerosis in patients with SLE should be evaluated because atherosclerosis is highly prevalent in SLE patients and PCSK9 inhibition has been suggested to be beneficial for this condition." (PMID 37964871, 2023). "If PCSK9 is silenced, it reduces the secretion of interleukin-1β, TNF-α, and monocyte chemoattractant protein 1 in the arteries of ApoE KO mice with atherosclerosis." (PMID 36831039, 2023). "PCSK9 has been demonstrated to modify LDL plasma levels and increase platelet activation, which promotes atherosclerosis, a defining feature of nearly all cardiovascular diseases." (PMID 36005422, 2022). "In this study, we aimed to evaluate the effects of PCSK9-i on CD34+CPCs and on early atherosclerosis damage, evaluated by pulse wave velocity (PWV) in a cohort of FH subjects." (PMID 35885020, 2022). "PCSK9 has been recently shown to bind directly to platelet CD36, triggering coagulation signaling cascades and enhancing ROS expression during atherosclerosis development." (PMID 36005422, 2022). "Therefore, Pcsk9 may be directly related to atherosclerosis development." (PMID 34044829, 2021). "In this study, we aimed to evaluate the effect of PCSK9-i on the inflammatory biomarkers NLR and MHR and on early atherosclerosis damage evaluated by pulse wave velocity (PWV) in a cohort of FH subjects." (PMID 33745063, 2021). "IL-4-reporter mice were injected with Pcsk9-AAV and fed WD for 16 weeks to promote atherosclerosis formation." (PMID 33720008, 2021). "A putative immunomodulatory role for PCSK9, unrelated to LDL-lowering, has also been recently highlighted in the context of atherosclerosis." (PMID 33677469, 2021).